GSK3B (glycogen synthase kinase 3 beta)
Diseases named in the same sentence as GSK3B in open-access papers (continued):
Sharing a sentence is not in itself a finding about the gene and the disease.
neuroblastoma (continued). "Another study also indicated that Nogo-66, an inhibitory domain of RTN4A, mediates glycogen synthase kinase-3β (GSK-3β) activation in mouse neuroblastoma cells." (PMID 35428758, 2022). "Here, overexpression of GSK3β in SH-SY5Y neuroblastoma cells increased not only the levels of tau phosphorylation, but also enhanced the cellular immunoreactivity to the tau oligomeric antibodies T22." (PMID 36232909, 2022). "We find that overexpression of GSK3β-induced phosphorylated 0N4R tau led to a higher level of tau oligomerization in SH-SY5Y neuroblastoma cells than wild type 0N4R, as determined by several orthogonal assays." (PMID 36232909, 2022). "Our study of pediatric neuroblastoma found that silencing bub1 led to increased expression of GSK3β and p-GSK3β and suppressed expression of p-GSK3β/GSK3β." (PMID 36237324, 2022). "Curcumin mitigates α-synuclein via the GSK-3β inhibition-mediated autophagy/lysosomal pathway in human neuroblastoma cells." (PMID 35883884, 2022). "Remarkably, the same compound proved to inhibit GSK-3β in human neuroblastoma SH-SY5Y cells at 1–5 μM concentrations and reduce τ phosphorylation at Ser396 in mouse hippocampal primary neurons at 20 μM." (PMID 34445804, 2021). "Up-regulation of this miRNA enhanced proliferation of neuroblastoma cells through targeting GSK3β and SFRP1." (PMID 33718173, 2021). "In this study, we have investigated the interaction between AChE and P‐tau in human neuroblastoma SH‐SY5Y cells by analyzing the effect of increased tau phosphorylation mediated by GSK3β on AChE mRNA and protein expression." (PMID 32955735, 2021). "It was reported that LY20314 (a GSK-3β inhibitor) inhibits cell proliferation in human neuroblastoma cell lines while increasing β-catenin levels." (PMID 34577571, 2021). "BMP-9 was reported to affect some aspects of AD and two small peptides derived from BMP-9 (pBMP-9 and SpBMP-9) induced the cholinergic differentiation via activation of PI3K/Akt and inactivation of GSK3β in SH-SY5Y neuroblastoma cells." (PMID 33723239, 2021). "GSK-3β inhibition in human neuroblastoma SH-SY5Y cells.Reduction of τ phosphorylation at Ser396 in mouse hippocampal primary neurons." (PMID 34445804, 2021). "Our results suggest that SIRT1 and AROS suppress GSK3β activity and acetylation, regulating the chemoresistance of doxorubicin in neuroblastoma." (PMID 32158616, 2020). "To test this, we used the highly transfectable neuroblastoma cell line neuro-2A (N2A) in experiments with overexpression and inhibition of miR-26a, which demonstrated the expected decrease and increase in GSK3β." (PMID 31964775, 2020). "WWOX has been shown to interact with and inhibit GSK3β, thereby increasing the microtubule assembly activity of Tau and promoting neurite outgrowth in human neuroblastoma SH-SY5Y cells." (PMID 32000863, 2020). "Taken together, our results suggest that SIRT1 and AROS inhibit GSK3β activity and provide additional insight into drug resistance in the treatment of neuroblastoma." (PMID 32158616, 2020). "We recently identified residue L130 of GSKIP as a critical point for binding with GSK3β, and the L130P GSKIP mutant resulted in loss of inhibition of neurite outgrowth in human neuroblastoma SH-SY5Y cells." (PMID 31640277, 2019). "Transfection of miR‐25 inhibitor or a Gsk3β overexpression plasmid attenuated the effects of SLC34A2 overexpression on the stemness of neuroblastoma cells." (PMID 30868061, 2019). "In xenografts of the murine neuroblastoma cell line N2A inhibition of GSK-3β reduces tumor growth by induction of G2/M cell cycle arrest." (PMID 31331081, 2019). "Our results demonstrate that miR‐25/Gsk3β‐mediated activation of Wnt signaling is responsible for SLC34A2‐induced enhancement of neuroblastoma cell stemness." (PMID 30868061, 2019). "Orphan nuclear receptor estrogen-related receptor gamma (ERR-gamma) induces GSK3β phosphorylation by upregulating PLK2 responsible for the differentiation of neuroblastoma SH-SY5Y cells." (PMID 29497051, 2018).
neuroblastoma (continued). "NBT treatment decreased the expression of a neuroblastoma-derived MYC (MYCN) and multidrug resistance-associated protein 1 (MRP1) as well as downregulating Akt, GSK3β, and β-catenin." (PMID 30486290, 2018). "Efficacy of the most active gRNA for Gsk3b (gRNA3) was further established, as compared to a scrambled gRNA, using a puromycin selection system in mouse neuroblastoma cells." (PMID 29706865, 2018). "We have reported that treatment of neuroblastoma cell lines with AR-A014418 reduced the growth and associated with reduction in the level of GSK-3α phosphorylation at Tyr279 compared to GSK-3β phosphorylation at Tyr219." (PMID 29751783, 2018). "As an example, we measured the effect of silencing of GSK3β overexpression by lentiviral transduction of a short hairpin for RNA interference (shRNAi) in an N2a neuroblastoma cell line." (PMID 28827685, 2017). "Co-immunoprecipitation showed that Drp1 binding to GSK-3β was increased after an oxygen-glucose deprivation/reperfusion (OGD/R) insult in cultured neuroblastoma cells." (PMID 28591721, 2017). "To evaluate the role of phosphorylation in tau aggregation at the cellular level, we co-transfected tau in human M17 neuroblastoma cells with 14-3-3ζ and either GSK3β or PKA." (PMID 27548710, 2016). "cAMP activates PKA and thereby stabilizes β-catenin either directly or indirectly by inhibiting GSK3β, resulting in increased β-catenin activity and neuroblastoma cell viability." (PMID 25266063, 2015). "It was described that the acute effect of Aβ on Gsk-3β activity (estimated by Ser9 phosphorylation) in human SH-SY5Y neuroblastoma cells is biphasic, with early activation after 1 h of incubation followed by inactivation after 24 h." (PMID 26334640, 2015). "We also demonstrated that AKT2 overexpression regulates the nuclear-cytoplasmic distribution of exogenous Gli1 protein in neuroblastoma cells by relieving a GSK3β-mediated destabilization of SUFU, a negative regulator of Gli1 nuclear translocation." (PMID 23900341, 2013). "It has been shown that GSK3β inhibition leads to G2/M accumulation and increased apoptosis in the neuroblastoma cell line SK-N-SH." (PMID 23251412, 2012). "For example, despite evidence for a substantial proapoptotic role of GSK-3β, it is the inhibition of GSK-3β that promotes apoptosis and decreases viability in neuroblastoma cells." (PMID 22675363, 2012). "We found that MK-801 inhibited the immediate KCl-induced dephosphorylation of AKT (Ser473) and GSK3β (Ser9) in SH-SY5Y neuroblastoma cells." (PMID 20046351, 2008). "Curcumin affected the expression of PS1 and GSK‐3β in cultured neuroblastoma cells." (PMID 40678834, 2025). "Interestingly, in a different study, TRF-treated neuroblastoma cells showed similar improvements in antioxidative and AD-related GSK3B and TAU protein markers (of tau hyperphosphorylation and neurofibrillary tangle formation) compared to controls." (PMID 40869012, 2025). "In this regard, both the PI3K/Akt and PLC/PKC pathways engaged by STX can promote the phosphorylation and inactivation of GSK3β, consistent with our data showing that STX induced a rapid increase in GSK3β phosphorylation in both MC65 neuroblastoma cells and hippocampal neurons." (PMID 41019780, 2025). "Thus, our data demonstrated that GSK3β plays a potential role in the phosphorylation of Ser129 α-Syn in H. pylori-infected and rotenone-treated neuroblastoma cells." (PMID 40988055, 2025). "The results showed that c-Jun overexpression inhibited the expression of β-catenin inside the nuclei and decreased the phosphorylation level of GSK3β at Ser9(pGSK3β(s9)), both of which play important roles in neuroblastoma cell proliferation and differentiation." (PMID 40149013, 2025).
neuroblastoma (continued). "Moreover, GSK3β inhibition has shown potential in reducing neuroblastoma cell viability and inducing cell death." (PMID 39192051, 2024). "Additionally, enrichment was seen in genes related to neuron fate commitment and specification, supported by the work in neuroblastoma cell lines that connected WWOX to GSK-3β and neuronal differentiation." (PMID 34831305, 2021). "Furthermore, in neuroblastoma cells, it was noted that miR-1303 targets both glycogen synthase kinase-3 beta (GSK3β) and secreted frizzled-related protein 1 (SFRP1), which are endogenous inhibitors of Wnt/β-catenin." (PMID 33435156, 2021). "Therefore, identifying the functional correlation between SIRT1 and GSK3β is important for the development of novel therapies for neuroblastoma." (PMID 32158616, 2020). "Accordingly, GSK3β inhibition has already shown anti-tumor potential with anti-proliferative and pro-apoptotic effects in neuroblastoma, BON-1, H727 and medullary thyroid carcinoma cells being accompanied by reduced expression of β-catenin and neuroendocrine tumor markers." (PMID 28800359, 2017). "Moreover, in neuroblastoma cells, valproate treatment activated Akt and subsequently augmented inhibitory phosphorylation of GSK3β." (PMID 29179438, 2017). "We have found that in human M17 neuroblastoma cells, tau phosphorylation by GSK3β or PKA does not cause tau aggregation, but promotes 14-3-3ζ-induced tau aggregation by destabilizing microtubules." (PMID 27548710, 2016). "Also, it is neuroprotective against mitochondrial oxidative stress in neuroblastoma SH-SY5Y cells via PI3K/Akt/GSK-3β pathway." (PMID 27378923, 2016). "To examine whether the overexpression of NCYM contributes to the chemosensitivity of neuroblastomas via GSK3β inhibition, we tested the effect of NVP-BEZ235 on the survival of the MYCN/NCYM double transgenic mice." (PMID 24391509, 2014). "In addition, GSK3β inhibition contributes to the inhibition of apoptosis in response to treatment with DNA-damaging drugs in neuroblastoma cells." (PMID 24391509, 2014). "It revealed that cyanidin-3-glucoside upregulated p-GSK3β (Ser 9) in a rat neuroblastoma cell line." (PMID 23864892, 2013). "Interestingly, insulin transiently promotes tau phosphorylation by activating GSK-3β in SH-SY5Y neuroblastoma cells and primary cortical neurons." (PMID 22536436, 2012). "Valproate was shown to inhibit GSK3 through a variety of mechanisms, such as serine phosphorylation, tau protein phosphorylation-mediated GSK3 inhibition in human neuroblastoma cell lines overexpressing GSK3β, or through the action of metabolites that potently inhibit GSK3 activity in vivo." (PMID 23449817, 2012). "Moreover, meth exposure increases GSK3β activity and decreases excitatory synapse density in the hippocampus of adult mice, with similar effects having been noticed in human neuroblastoma cells where meth treatment increases tau phosphorylation and GSK3β activity." (PMID 37691228, 2024). "Thus, we assumed that SLC34A2 might promote the stemness of neuroblastoma cells through miR‐25/Gsk3β‐mediated activation of Wnt signaling." (PMID 30868061, 2019). "In neuroblastoma SH-SY5Y cells exposed to hyperglycemia, a condition known to increase GSK3β activity, melatonin exerted an inhibitory effect on the GSK3β signaling pathway, likely through the activation of its melatonin receptor." (PMID 39128995, 2025). "Treatment of the AD SH-SY5Y (human neuroblastoma cells) cell model with DPEO resulted in decreased intracellular levels of Aβ, GSK-3β, P-Tau, IL-1β, TNF-α, IL-6, COX-2, OFR, and HFR, alongside reduced AchE and BchE activities and increased SOD activity." (PMID 39056736, 2024). "We have also proposed to combine Didymin with PD-L1 mAbs due to implications between RKIP and PD-L1 through EMT factors, GSK3β signaling, and N-MYC in treatments of neuroblastoma." (PMID 38786085, 2024).
neuroblastoma (continued). "We propose that in the case of neuroblastoma, inhibition of AKT activity blocks its ability to phosphorylate (and thereby inhibit) its substrate, GSK3β." (PMID 38413795, 2024). "In a human neuroblastoma cell line (SH-SY5Y), FeSO4 can activate GSK-3β, and down-regulate the phosphorylation of GSK-3β." (PMID 36829936, 2023). "NYCM was found to co-immunoprecipitate with MYCN and kinase GSK3B, which natively phosphorylates MYCN to target it to the proteasome for degradation, in both neuroblastoma and bladder cancer lines." (PMID 35451603, 2022). "Later on, research in SH-SY5Y neuroblastoma cells showed that WWOX physically interacts with and inhibits GSK-3β, preventing Tau hyperphosphorylation." (PMID 34831305, 2021). "Our own in house data show that purified P. gingivalis lipopolysaccharide (LPS) application to a neuroblastoma cell line, in vitro cell model also activated the PI3K/AKT pathway in which glycogen synthase kinases-3 beta (GSK-3β) mRNA expression increased." (PMID 33062201, 2020). "In this study, we identified a specific PKA phosphorylation site on Tau protein that was accompanied by GSK3β and GSKIP to form a working complex from the neuroblastoma cell line in clinical AD patients." (PMID 31640277, 2019). "We previously identified residue L130 of GSKIP as being critical for binding with GSK3β, and cells with the L130P GSKIP mutant lose the inhibition of neurite outgrowth in human SH-SY5Y neuroblastoma cells." (PMID 31640277, 2019). "CREB DNA binding activity is inhibited by GSK-3β overexpression and increased by lithium or sodium valproate which are GSK-3 inhibitors in human neuroblastoma cells." (PMID 27049759, 2016). "Stimulation of neuroblastoma cells with forskolin or PGE2 increased p-GSK3β (ser9) and elevated levels of unphosphorylated β-catenin at the GSK3β residues." (PMID 25266063, 2015). "Neuroblastoma cells stimulated with forskolin or PGE2 were analysed for protein levels of phosphorylated β-catenin and GSK3β." (PMID 25266063, 2015). "Here, we identified high levels of phosphopeptides from downstream mediators of these pathways, including PI3K p85β, PDK1, GSK3β, MEK2, ERK1, and ERK2, in MYCN-amplified neuroblastoma cells." (PMID 24349301, 2013). "In cell culture studies, apoptosis was either attenuated or fully abrogated by inhibiting GSK-3β in primary neurons, HT-22 cells, PC12 cells, and human SH-SY5Y neuroblastoma cells." (PMID 22675363, 2012). "We found that GSK-3β overexpression suppressed the expression of PME-1, as measured both at the mRNA level and the protein level, suggesting that GSK-3β suppresses the expression of PME-1 in human neuroblastoma cells." (PMID 31714894, 2019). "In human non–small-cell lung cancer cell lines, degradation of cellular FLICE-inhibitory protein by celecoxib is mediated by GSK3 but not Akt78, and in murine neuroblastoma cells, estradiol regulates GSK3β activity independent of Akt79." (PMID 28484273, 2017). "However, as shown in neuroblastoma, Gli1 activity is suppressed by AKT2 which phosphorylates GSK3β, leading to GSK3β stabilizing the inhibitory SUFU/GLI1 complex." (PMID 26512695, 2015). "This positive autoregulatory loop may function in primary human neuroblastomas to enhance metastasis as well as drug resistance through stabilization of MYCN and even β-catenin, which are mediated by inhibition of GSK3β." (PMID 24391509, 2014). "Furthermore, NCYM co-immunoprecipitated with GSK3β and substrates of GSK3β such as MYCN and β-catenin were stabilized in the neuroblastoma tissues induced in MYCN/NCYM transgenic mice." (PMID 24391509, 2014). "Furthermore, the survival of MYCN transgenic mice bearing neuroblastoma was improved by treatment with NVP-BEZ235, a dual PI3K/mTOR inhibitor shown to destabilize MYCN via GSK3β activation." (PMID 24391509, 2014).
neuroblastoma (continued). "In neuroblastoma cell lines showed that clozapine increased Ser9 phosphorylation of GSK3β via the activation of the canonical Wnt pathway, but not via the activation of the PI3K/Akt pathway." (PMID 23449817, 2012). "Similarly, GUO protects SH-SY5Y neuroblastoma cells against β-amyloid toxicity, by decreasing the formation of early ROS and against the mitochondrial oxidative stress, induced by the blockage of mitochondrial complexes, by inducing HO-1 via PI3K/Akt/GSK-3β." (PMID 27378923, 2016). "To examine if the PI3K activator peptide can modulate GSK3β phosphorylation, we took advantage of a PI3K previously characterized activation peptide (PTD4-PI3KAc;) and quantified the levels of p-S473AKT and p-S9GSK3β, on SH-SY5Y human neuroblastoma cell line cultures." (PMID 25764078, 2015). "Unlike some other neurons, the SH-SY5Y neuroblastoma cell line can store glycogen and expresses two GSK3 isoforms—GSK3α and GSK3β." (PMID 37512524, 2023). "For these experiments, here we have treated human neuroblastoma SH-SY5Y cells, with the non-ATP competitive GSK-3β inhibitor Tideglusib or with the widely used ATP competitive inhibitor SB216783." (PMID 34445680, 2021).